MYC (MYC proto-oncogene, bHLH transcription factor)
Diseases named in the same sentence as MYC in open-access papers (continued):
Sharing a sentence is not in itself a finding about the gene and the disease.
gastric cancer (continued). "In clinical studies of gastric cancer (GC), NSCLC, and melanoma, elevated expression of glycolysis-related molecules lactate dehydrogenase A and oncogene c-Myc (MYC) correlated with resistance to PD-1 blockade." (PMID 41281945, 2025). "Finally, gastric cancer is characterized by pronounced molecular heterogeneity and a complex immune microenvironment, which may affect the efficacy of targeting the FMR1/c-MYC axis." (PMID 41184982, 2025). "Therefore, NCAPD3 knockdown may inhibit CCND1, MYC, and ESR1 expression to downregulate CDK6 and IRSI expression, thereby inhibiting the proliferation of gastric cancer cells." (PMID 38711992, 2024). "For example, in the gastric cancer cell line, SNU16, at least three distinct species of ecDNA exist independently from chromosomes; those that localize the MYC (chr 8) oncogene, those that localize the FGFR2 (chr 10) oncogene, and those that co-localize MYC (chr 8), FGFR2 and CD44 (chr 11) genes." (PMID 39091515, 2024). "Therefore, NCAPD3 knockdown may inhibit CCND1, MYC, and ESR1 activity to downregulate CDK6 and IRS1 expression, thereby inhibiting the proliferation of gastric cancer cells." (PMID 38711992, 2024). "The expression of MYC proto-oncogene, as well as bHLH transcription factor (MYC) and its target, snail family transcriptional repressor 1 (SNAI1), is inhibited when circ-TNPO3 sequesters IGF2BP3, which reduces the ability of gastric cancer cells to proliferate and metastasize." (PMID 38003674, 2023). "For example, circ-TNPO3 can interact with IGF2BP3 to weaken the role of IGF2BP3 in stabilizing MYC mRNA, thereby regulating the MYC-SNAIL axis and inhibiting the proliferation and metastasis of gastric cancer (GC)." (PMID 36139074, 2022). "Thus, in gastric cancer cells, it was shown that the RNA circHECTD1 binds miR-1256, thus activating expression of the USP5 gene which in turn leads to stabilization of β-catenin which activates expression of the MYC gene." (PMID 34440124, 2021). "It is likely that such low-level amplification is often not MYC specific, but may result from gross chromosomal gains of 8q that belong to the most frequent alterations in gastric cancers." (PMID 25649416, 2015). "Intra-tumor heterogeneity is a potential cause for failure of targeted therapy in gastric cancer, but the extent of heterogeneity of established (HER2) or potential (EGFR, CCND1) target genes and prognostic gene alterations (MYC) had not been systematically studied." (PMID 25649416, 2015). "In our study, the expression of transcription factors Oct4, Sox2, c-MYC, Nanog and SALL4 as well as the ability to differentiate into adipocytes in gastric cancer cells were enhanced by low level of DIM, suggesting that low level of DIM may affect gastric cancer cell reprogramming." (PMID 26918831, 2016). "However, our own data indicate that ACP-02, which has the highest BRD4 and c-MYC levels are less sensitive to BET inhibition and there seems to be little correlation between BRD4 levels and MYC regulation and antiproliferative effect in the Asian gastric cancer cell lines." (PMID 27259267, 2016). "To rule out interference from the MYC tag, we performed Co-immunoprecipitation (Co-IP) experiments using an anti-NUSAP1 antibody in 5-FU-resistant gastric cancer cells." (PMID 40393971, 2025). "MYC increases PHF8 protein levels rather than mRNA expression via stabilizing miR-22-3p, promoting the proliferation and migration or invasion of gastric cancer cells." (PMID 39311138, 2024).
gastric cancer (continued). "In gastric cancer (GC), since miR-3648 represses the WNT/β-catenin pathway via the inhibition of GSK-3-binding FRAT1/2 proto-oncogenes, its downregulation resulted in the upregulation of the WNT/β-catenin pathway, followed by the overexpression of MYC as a downstream effector." (PMID 37443779, 2023). "Indeed, in a gastric cancer cell line, where FGFR2 ecDNA and MYC ecDNA are in a hub, interference of FGFR2 enhancers decreased MYC expression, but interference of MYC enhancers did not affect FGFR2 expression." (PMID 37415185, 2023).
glioma (399 papers, 2008 to 2026). A benign or malignant brain and spinal cord tumor that arises from glial cells (astrocytes, oligodendrocytes, ependymal cells). "MYC functions as a key transcriptional regulator of cell growth and metabolic reprogramming and has been consistently associated with high-grade gliomas, including GBM." (PMID 40649712, 2025). "BRD4 has been implicated previously as a driver of glioma progression, potentially through promotion of MYC-driven anabolic pathways." (PMID 41187221, 2025). "Transgenic expression of MYC in mouse astrocytic lineages is sufficient to cause gliomas that resemble the human disease." (PMID 39184078, 2024). "SRY-box transcription factor 2 (SOX2), epidermal growth factor receptor (EGFR), and Myc proto-oncogene (MYC) are genes whose upregulation is associated with glioma stemness." (PMID 39419964, 2024). "Although the higher expression of MYC is associated with the higher-grade gliomas, our survival analysis reports better prognosis with higher MYC expression, when stratifying for tumour grade." (PMID 37400829, 2023). "On the other hand, Hoxa5 and Fabp4, both associated with increased malignancy in gliomas, were upregulated in MYC/SMARCA4 tumors." (PMID 37919824, 2023). "Of interest is the role of MYC proteins in the progression and malignancy of IDHmut gliomas, with MYC activation associated with progression from low grade glioma to high-grade GBM." (PMID 35467128, 2022). "TRIM3, an NHL- and filamin-domain-containing TRIM protein seems to exert a tumor suppressor role in glioma cells linked to the control of c-MYC, restoration of asymmetric cell division and attenuation of Notch Nuclear Transport." (PMID 36139694, 2022). "Our studies indicated cell senescence-associated genes such as PTTG1 and MYC influenced the activities of glioma cell obviously." (PMID 36527013, 2022). "For example, there is a positive correlation between the expression of FUBP1 and c-MYC in glioma and high expressions of FBP1 and c-MYC are associated with poor prognosis." (PMID 34116677, 2021). "As an example, miRNA-9 transported by glioma-derived exosomes is upregulated by MYC and OCT4 in GBM cells and causes the dysfunction of the Hypoxia-Inducible Factor (HIF)-1α/VEGF signaling pathway." (PMID 33328891, 2020). "A recent Turkish study of glioma cases showed some evidence of differential MYC expression depending on risk variant carriership indicating a regulation of the MYC locus." (PMID 31842352, 2019). "Another study of recurrent IDH mutant gliomas showed that the myelocytomatosis (MYC) signaling pathway is associated with tumor progression." (PMID 29156679, 2017). "Observation of the same effect in two different histologies, both of which are IDH-mutation driven, further supports this MYC dependent explanation of the 8q24.21-association in gliomas." (PMID 27282637, 2016). "C-MYC is essential for glioma cell cycle progression and proliferation and loss of c-MYC abrogates their tumorgenic potential." (PMID 24143218, 2013). "We also demonstrated using ChiP that FOXP3 is a transcriptional regulator of p21 and c-MYC supporting the idea that dysregulated expression of these factors is a major mechanism of tumorigenesis driven by the loss of FOXP3 expression in gliomas." (PMID 23888189, 2012). "However, R-2HG inhibits FTO in glioma, causing MYC/CEBPA mRNA methylation, disrupting the stability of these oncogene transcripts and inhibiting the activation of downstream oncogene pathways." (PMID 40469294, 2025). "MYC’s ability to transcriptionally activate ER stress response genes positions it as a crucial node integrating proliferative signaling with proteostasis mechanisms, particularly in the context of aging-associated glioma aggressiveness." (PMID 40718795, 2025). "Similarly, blocking the FTO/m6A/MYC/CEBPA-associated signaling pathway using R-2HG has shown promise in inhibiting the rapid development of glioma." (PMID 38649363, 2024).
glioma (continued). "In this regard, smoking is associated with an increased risk of glioma, and several studies exploring the molecular mechanisms involved in cigarette smoke-mediated cell proliferation have highlighted the upregulation of the c-MYC protein." (PMID 38333013, 2024). "Finally, in glioma, the rs55705857 SNP in the intronic region of the CCDC26 gene adjacent to MYC is not only associated with IDH-mutated gliomas but also appears to confer enhanced MYC activity, potentially affecting its transactivation ability." (PMID 37443779, 2023). "In addition, we used GSEA to evaluate the related biological functions in glioma and found that the most enriched pathways were related to hallmark oxidative phosphorylation, adipogenesis, hedgehog signaling and MYC target V in the low m6A group." (PMID 35559019, 2022). "Interestingly, a strong association has been shown between 1p/19q co-deleted IDH-mutated gliomas and SNPs mapping to the 8q24 locus, which is rich in long non-coding RNA that may modulate MYC expression." (PMID 27090007, 2016). "c-MYC amplification has also been shown to increase the sensitivity of PLK1 inhibitors in glioma and medulloblastoma." (PMID 41458961, 2025). "Transfection of c-MYC into glioma cells with low c-MYC expression not only upregulated PLK1 expression but sensitized glioblastoma cells to volasertib." (PMID 41458961, 2025). "Our data identify MYC as a pivotal transcriptional regulator of the ESURATAG gene set, aligning with previous research establishing MYC’s role in driving tumor onset and progression in gliomas." (PMID 40718795, 2025). "Prior studies have demonstrated that in low‐grade IDH‐mutant gliomas, TERTp mutation is associated with genetic alterations in CIC, FUBP1, and MYC, as these genes are closely related to 1p/19q deletion." (PMID 39804195, 2025). "Our findings complement the notion of MYC’s involvement in cell cycle progression in gliomas and expand the scope of MYC-driven oncogenic programs to include ER stress and proteostasis pathways." (PMID 40718795, 2025). "Among BET family members, BRD4 plays a notable role in glioma progression and malignancy, particularly in R132H IDH mutants, where MYC activation is associated with transformation into higher-grade GBMs." (PMID 40565099, 2025). "MYC has been shown to regulate cell cycle progression-driven tumor aggressiveness in gliomas, aligning with our findings that cell cycle progression-related gene signatures are enriched in patients having high ESURATAG-GS scores." (PMID 40718795, 2025). "The c-MYC oncogene is variably expressed across different brain tumors types, e.g., in about 70% of glioma, including low and high grade tumors, and is amplified in up to 17% of group 3 medulloblastomas, the most common malignant brain tumor in children." (PMID 40917877, 2025). "In line with this, ESURATAG-GS is enriched in glioma patients having high MYC-GS (comprising of list of genes potentially regulated by MYC) scores compared to those having low scores." (PMID 40718795, 2025). "A separate study by Li and colleagues found that Beta2-Microglobulin in glioma stem cells promoted an increased release of TGF-β1 from glioma cells via activation of the PI3K/AKT/MYC axis." (PMID 38523840, 2024). "Analysis of TCGA and Chinese Glioma Genome Atlas (CGGA) datasets revealed that RBBP6 mRNA levels were positively correlated with MYC mRNA levels." (PMID 38503731, 2024). "In astrocytomas, a subset of gliomas characterized by mutations in the isocitrate dehydrogenase (IDH) gene, relative MYC overexpression is one of the core driver events." (PMID 38877600, 2024). "There is experimental evidence that MYC plays a role in maintaining glioma cancer stem cells and regulating intercellular competition during early stages of gliomagenesis." (PMID 38877600, 2024). "Stemness-related genes, such as SOX2 and POUF2, are essential for glioma propagation, and MYC regulates the expression of these genes in glioma cells." (PMID 39501082, 2024).
glioma (continued). "H3-K27M gliomas show high expression of MYC and MYC target genes, due to both epigenetic alterations and structural variants, resulting in a viability dependency on MYC signaling." (PMID 39093942, 2024). "H3-K27M gliomas are characterized by deregulation of histone acetylation and methylation pathways, as well as the oncogenic MYC pathway." (PMID 39093942, 2024). "We also observed regional heterogeneity in genes associated with poor clinical prognosis in IDH-mutant glioma, including CDKN2A/B, CDK4, MYC, MYCN, and PDGFRA23." (PMID 37770427, 2023). "TRMT6 also predicted poorer prognosis in glioma and promoted glioma cell proliferation, migration, and invasion by regulating cell cycle, MYC, TGF-β, PI3K-AKT, NOTCH, and MTORC1 pathways." (PMID 37612540, 2023). "Cell-based experiments validated that the overexpression of c-MYC rescued the inhibition of cell proliferation, migration, and invasion caused by MAD2L2 silencing in glioma cells, and vice versa." (PMID 38017538, 2023). "In C6 glioma cells, a parallel reduction was observed in gene expression levels of c-MYC and BCL2 after transfection with the miRNAs named vvi-miR396b, ptc-miR396f, and ptc-miR396f, compared to non-targeting controls." (PMID 37542285, 2023). "Genetic or pharmacologic targeting neddylation has previously been shown to upregulate PD-L1 expression in gliomas via MYC." (PMID 37031300, 2023). "Through in vitro and in vivo experiments, we confirmed that MAD2L2 promotes the maintenance of stemness and malignant behaviors in glioma, and the oncogene c-MYC plays a crucial role in these processes." (PMID 38017538, 2023). "IL-11 secreted by microglia activates STAT3 signaling pathways, leading to increased MYC expression, and MYC overexpression transforms glioma cells into a stem cell state, thereby enhancing tumorigenicity and TMZ resistance." (PMID 37700840, 2023). "To investigate the potential role of c-MYC in mediating the function of MAD2L2 in glioma cells, we performed additional experiments." (PMID 38017538, 2023). "BPTF maintains the self-renewal potential of glioma stem cells by promoting the transcriptional activation of the MYC gene and its downstream targets." (PMID 36967443, 2023). "Sensitivity to glutamine deprivation is c-MYC-dependent in glioma cells and can be suppressed by targeting MYC expression." (PMID 36959802, 2023). "Since the permeability of WP1066 through the blood-brain barrier has been demonstrated in glioma models, we next tested its therapeutic efficacy in an orthotopic xenograft model of MYC-driven MB." (PMID 37190167, 2023). "In their study, they found a new feedback pathway that can regulate glioma cell proliferation and tumorigenesis, the MYC-miRNA-MXI1 pathway." (PMID 35688823, 2022). "Mechanistically, TRIM66-induced upregulation of GLUT3 protein was shown to be a result of the binding of c-MYC on SLC2A3/GLUT3 promoters in glioma cells." (PMID 36139694, 2022). "Accordingly, Wang and coworkers demonstrated that MYC is required for regulating the proliferation and survival of glioma CSCs." (PMID 36361720, 2022). "In conclusion, MZF1, an oncogenic transcription factor, promotes glioma proliferation by inducing c-MYC expression." (PMID 36499054, 2022). "GSEA showed that hallmark oxidative phosphorylation, adipogenesis, hedgehog signaling and MYC target V1 were significantly enriched in glioma patients in the low m6A group." (PMID 35559019, 2022). "Downregulated genes common to different glioma cell cultures are enriched in transcripts controlled by MYC and MAX." (PMID 36231068, 2022). "IHC staining was performed to detect the representative PTTG1 and MYC protein levels in gliomas and peritumor tissues (15 cases) of The Second Hospital of Shandong University." (PMID 36527013, 2022).